PROK2 (prokineticin 2)
Diseases named in the same sentence as PROK2 in open-access papers (continued):
Sharing a sentence is not in itself a finding about the gene and the disease.
Chronic colitis (1 paper, 2023). A chronic inflammatory disease of the large intestine (colon, cecum and rectum). "We found that IHC expression of AQP9 and PROK2 in CD tissues was higher than that in chronic colitis tissues." (PMID 36792688, 2023).
COVID-19 (1 paper, 2024). A disease caused by infection with severe acute respiratory syndrome coronavirus 2. "A weighted gene co‐expression network analysis (WGCNA) of RNA-sequencing dataset revealed four key genes, PROK2, IL6, TNF, SLC7A11, closely related to COVID-19 ALI41." (PMID 38769293, 2024).
endometrial polyp (1 paper, 2025). A benign nodular lesion protruding above the surface of the endometrium. "Overall, the figure suggests that while PROKR1 and PROKR2 show the most significant changes, other genes like PROK1, PROK2, and HOXA10 exhibit smaller or non-significant alterations, highlighting the importance of certain prokineticins in the pathology of endometrial polyps." (PMID 39915377, 2025).
Huntington disease (1 paper, 2015). Huntington disease (HD) is a rare neurodegenerative disorder of the central nervous system characterized by unwanted choreatic movements, behavioral and psychiatric disturbances and dementia. "The five genes (PROK2, ZNF238, AQP9, CYSTM1 and ANXA3) that were validated independently in both cohorts present a candidate biomarker panel for stage determination and therapeutic readout in Huntington's disease." (PMID 25626709, 2015).
Hypertension (1 paper, 2016). The presence of chronic increased pressure in the systemic arterial system. "The difference in serum prokineticin-2 levels in patients with and without hypertension was also not significant (7.00 ± 3.24 ng/ml, n = 106, vs 6.76 ± 3.12 ng/ml, n = 56, P = 0.662)." (PMID 26728949, 2016).
hypospadias (1 paper, 2017). Hypospadias is the displacement of the urethral meatus on the ventrum of the penis. "We conclude that variants in CHH genes, in particular PROKR2, PROK2, WDR11 and FGFR1 with CHD7, may contribute to under-virilisation phenotypes including hypospadias in Indonesian boys." (PMID 28209183, 2017). "We postulate that variants in CHH genes, in particular PROKR2, PROK2, WDR11 and FGFR1 with CHD7, may contribute to under-virilisation phenotypes including hypospadias in Indonesia." (PMID 28209183, 2017).
influenza infection (1 paper, 2024). "As expected, CXCL10 and IFNα levels were highest in influenza infection, whereas IL6, IL10, IL1β, and PROK2 (which is highly inducible in macrophages by LPS and other TLR2/4 agonists) reached higher levels in the bacterial infections." (PMID 39395995, 2024).
ischemic stroke (1 paper, 2018). A stroke disorder caused by obstruction of blood flow to the brain, due to thrombotic (local blood clot formation) or embolic (due to a blood clot or other material traveling from another site) event. "Some of the top20 most changed genes are already known to be relevant to the ischemic stroke physiopathology (e.g. Il-1R, Nos2, Prok2)." (PMID 30439964, 2018).
lung adenocarcinoma (1 paper, 2020). A carcinoma that arises from the lung and is characterized by the presence of malignant glandular epithelial cells. "In human lung adenocarcinoma tissues, Bv8/Prok2 was detected in infiltrating neutrophils." (PMID 32422991, 2020).
Merkel cell carcinoma (1 paper, 2020). "PROK2 expression is upregulated in cases of human Merkel cell carcinoma (MCC) containing the MC polyomavirus (MCpyV)." (PMID 33121134, 2020).
metabolic syndrome (1 paper, 2016). A cluster of metabolic risk factors for CARDIOVASCULAR DISEASES and TYPE 2 DIABETES MELLITUS. "It is also unclear if the relationship between prokineticin-2 and metabolic syndrome is primary or secondary to other proinflammatory cytokines and/or adipokines." (PMID 26728949, 2016).
methamphetamine dependence (1 paper, 2011). A drug dependence that is a psychological dependency on the regular use of methamphetamine. "To evaluate the association between PROK2 and methamphetamine dependence, we conducted a case-control study of Japanese samples (215 methamphetamine dependence and 232 controls) with four tagging SNPs selected by HapMap database." (PMID 21886578, 2011). "These evidences indicate that PK2 gene (PROK2) is a good candidate gene for the pathogenesis of methamphetamine dependence." (PMID 21886578, 2011). "We did not detect an association between PROK2 and Japanese methamphetamine dependence patients in allele/genotype-wise analysis, or the haplotype analysis." (PMID 21886578, 2011). "Our findings suggest that PROK2 does not play a major role in the pathophysiology of methamphetamine dependence in the Japanese population." (PMID 21886578, 2011).
neuroblastoma (1 paper, 2023). Neuroblastoma (NB) is the most common solid, extracranial childhood tumor. "In neurons, PROK1, but not PROK2, enhances cell migration of the human neuroblastoma cell line SK-N-SH at high concentrations (400 nM)." (PMID 37895111, 2023).
promyelocytic leukemia (1 paper, 2022). "To further investigate the effects of Fth1/Prok2 on the immune function of neutrophils, we adopted recombinant lentiviral vector of Fth1/Prok2 shRNA and human promyelocytic leukemia (HL-60) cell-derived neutrophils." (PMID 36513690, 2022).
psoriasis (1 paper, 2022). An autoimmune condition characterized by red, well-delineated plaques with silvery scales that are usually on the extensor surfaces and scalp. "Recent studies have found that certain factors regulate the AIM2 inflammasome signaling pathway and participate in the pathogenesis of psoriasis, including prokineticin 2 (PK2), caspase recruitment domain family member 18 (CARD18), aurora kinase A (AURKA), TLR-7, TLR-8, and TLR-9 antagonists." (PMID 36118867, 2022).
psychosis (1 paper, 2011). "Therefore, we reasoned that PROK2 may not play an important role in the pathophysiology of METH dependence and METH-induced psychosis in the Japanese population." (PMID 21886578, 2011).
pubertal delay (1 paper, 2025). "A family history of pubertal delay was identified in 2 patients with VUS variants in PROK2 and IL17RD." (PMID 40508017, 2025).
ulcerative colitis (1 paper, 2024). An inflammatory bowel disease involving the mucosal surface of the large intestine and rectum. "Other genes identified within the human IBD ‘granulocyte, myeloid’ module, including NOD2, FCGR3 and PROK2, which were most highly expressed in the biopsies from ulcerative colitis, were most highly abundant in the Maffl/flCd4Cre mice." (PMID 38609547, 2024).
tumor (122 papers, 2008 to 2025). "Our previous study found that PROK2 expression is associated with angiogenesis and tumor formation in CRC." (PMID 30046389, 2018). "Also, CXCL1 causes the recruitment of neutrophils into the tumor niche; these cells secrete prokineticin-2, which causes tumor cell migration and subsequent metastasis." (PMID 40427171, 2025). "The significance of PROK2 in the tumor microenvironment has been highlighted by the present study, providing novel insight for the elucidation of the molecular mechanism underlying tumor invasion and metastasis for the development of a new therapy for CRC." (PMID 30046389, 2018). "Mouse models for CRC genetic aberrations have demonstrated resistance to anti-VEGF antibodies due to tumor-infiltrating neutrophils that overexpresses angiogenesis-related Bv8/PROK2." (PMID 40777019, 2025). "Elevated plasma Bv8/PROK2 levels correlated with poor overall survival patients by suppressing these tumor-infiltrating neutrophils and the related angiogenic processes, restoring sensitivity to anti-VEGF therapies." (PMID 40777019, 2025). "These N2-like TANs expressed Prok2, which binds Prokr1 on 4T1 tumor cells, supporting metastatic outgrowth and angiogenesis." (PMID 40805288, 2025). "Angiogenic factors, such as VEGF, Angiopoietin 2 (ANG2) and prokineticin 2 (PROK2) correlate with tumor aggressiveness." (PMID 39050569, 2024). "Neutrophils release a variety of factors, including NE, MMPs, ROS, VEGF, and prokineticin-2 (Bv8), all of which can influence tumor development." (PMID 39795864, 2024). "Recent studies revealed that Bv8, also known as prokinectin 2 (Prok2), regulates myeloid-cell-dependent tumor angiogenesis." (PMID 37090721, 2023). "In several murine transplantable models of cancer, MDSC were found to be the predominant source of prokineticin-2 (Bv8), a secreted protein involved in tissue-specific angiogenesis, which promoted vessel formation and tumor growth." (PMID 37234993, 2023). "In the lungs, tumor-derived G-CSF also mobilizes granulocytes to pre-metastatic niches and supports subsequent metastasis formation, whereas prokineticin-2 aids tumor cell migration through the activation of prokineticin receptor." (PMID 36294305, 2022). "For example, tumor-infiltrating neutrophils produced the Bv8/PROK2 protein, which caused the refractoriness to anti-VEGF therapy in tumor allograft and xenograft models." (PMID 35664746, 2022). "Neutrophils increase the expression of BV8 (prokineticin-2) via CSF3, which causes myeloid cell mobility and myeloid-dependent tumor angiogenesis." (PMID 36419156, 2022). "Several laboratory studies have demonstrated that stromal cells, such as fibroblasts and myeloid cells, can promote tumor angiogenesis via expressing various pro-angiogenic factors, such as Bv8/PROK2, members of the VEGF, FGF, PDGF, and angiopoietin families." (PMID 36419156, 2022). "By releasing proangiogenic factors, including vascular epidermal growth factor (VEGF) and prokineticin-2 (also known as Bv8), MDSCs support tumour angiogenesis and vasculogenesis and promote both stemness and the proliferation of cancer cells." (PMID 34685679, 2021). "PROK2 has been reported to act as an important factor in the creation of tumor microenvironment favoring tumor development and progression." (PMID 32887509, 2020). "Tumor cell implantation induced G–CSF expression in mice and eventually augmented the expression of Bv8/Prok2 in CD11b+Gr1+ neutrophils." (PMID 32422991, 2020). "MDSCs promote angiogenesis also via expression of a prokineticin 2, known as Bv8, which plays an important role in myeloid cell-mediated tumor angiogenesis." (PMID 31057536, 2019). "In response to CSF3, neutrophils upregulate the expression of BV8 (also known as prokineticin-2) that induce myeloid cell mobilization and myeloid-dependent tumor angiogenesis." (PMID 29675018, 2018).
tumor (continued). "In these pre-metastatic niches, factors are produced to attract and later on arrest tumor cells such as IL-1β, prokineticin 2, and MMPs while neighboring cells are stimulated to secrete VEGF to facilitate the arrival of tumor cells." (PMID 30233579, 2018). "The findings of our present and previous study show that PROK2 expression is highly correlated with angiogenesis, tumor formation, and liver metastasis through in vitro and in vivo assays." (PMID 30046389, 2018). "Regarding malignant tumors, some reports have shown that PROK2 is related to angiogenesis in glioblastomas and hepatocellular carcinomas, cell infiltration in pancreatic cancer, and tumor development in prostate cancer." (PMID 30046389, 2018). "This suggests that in CRC, the tumor itself organizes the surrounding environment via PROK2 expression, which plays a significant role within the tumor microenvironment." (PMID 30046389, 2018). "PROK2 is a key regulator of inflammation-dependent tumorigenesis promoting chemotaxis, angiogenesis and drug-resistance into the tumor microenvironment." (PMID 26967390, 2016). "Yan et colleagues have also reported that IL-6 cooperates with G-CSF to induce tumor function of murine neutrophils in BM by modulating signaling pathways that favor tumor angiogenesis through up-regulation of PROK2." (PMID 26967390, 2016). "In contrast, after the PROK2 gene vector was transfected, the size of tumor mass was 73.6 mm3 in DLD-1, 201.4 mm3 in HCT116, and 86.3 mm3 in HT29, showing a significant increase in tumor mass formation." (PMID 26317645, 2015). "Notably, the proportion of neutrophils increased in the metastatic samples, transcriptionally resembling tumor-associated neutrophils (TAN), with a high expression of VEGFA, LGALS3, OLR1, PROK2, MMP9, and IL1RN." (PMID 38358826, 2024). "Furthermore, prokineticin 2 (Bv8) triggers neutrophil-dependent angiogenesis, and inhibition of Bv8 activity limits angiogenesis and tumor development." (PMID 36060811, 2022). "Prokineticin 2(PROK2)is an important contributor to tumor angiogenesis, Ring Finger Protein 213 (RNF213) is essential for normal vascular development, and Leucine Rich Alpha-2-Glycoprotein 1 (LRG1) plays a role in retinal vascularization abnormalities observed in oxygen-induced retinopathy." (PMID 36032067, 2022). "Furthermore, TANs secrete HGF and high levels of prokineticin 2 (Bv8), a potent mitogenic factor for endothelial cells and the main angiogenic factor in neutrophil-dependent tumor angiogenesis." (PMID 36555469, 2022). "Prokineticin 2 (PROK2) is reported to be involved in tumor progression in some malignant tumors." (PMID 32887509, 2020). "Moreover, anti-Bv8/Prok2 antibodies reduced neutrophils in peripheral blood and tumor sites and suppressed tumor angiogenesis, thereby inhibiting tumor growth." (PMID 32422991, 2020). "The same group further claimed that enhanced Bv8/Prok2 expression in neutrophils could account for frequently observed refractoriness to anti-VEGF therapy in tumor-bearing mice." (PMID 32422991, 2020). "PROK2 expression was positively correlated with tumor-node-metastasis (TNM) stage." (PMID 32887509, 2020). "Moreover, in a tumor xenograft model, granulocyte colony-stimulating factor (G-CSF)-induced upregulation of Bv8 (known as prokineticin-2) in neutrophil was shown to promote tumor angiogenesis." (PMID 30691207, 2019). "Prokineticin 2 (PROK2) may be associated with angiogenesis and tumor formation in some malignant tumors." (PMID 30046389, 2018). "The polypeptide chemokine PK2 (Bv8, PROK2) has been shown to regulate myeloid cell mobilization from the bone marrow, leading to activation of the angiogenic process, as well as accumulation of macrophages and neutrophils in the tumor site." (PMID 23372791, 2013). "For example, the use of anti-G-CSF or anti-Bv8/PROK2 antibodies has been demonstrated to enhance the efficacy of anti-VEGFR2 therapy, providing a more comprehensive approach to inhibition of tumor angiogenesis." (PMID 40050933, 2025).
tumor (continued). "Neutrophils promote tumor progression by releasing angiogenic factors, including vascular endothelial growth factor (VEGF), matrix metalloproteinase 9 (MMP-9) and prokineticin-2 (PROK2)." (PMID 38303053, 2024). "Anti-VEGF therapy, in combination with anti-G-CSF or anti-Bv8/PROK2 antibodies, was demonstrated to efficiently suppress tumor growth." (PMID 35158807, 2022). "MDSCs also support tumor progression by inducing tumor angiogenesis through the release of VEGF, basic FGF (bFGF), prokineticin 2 (Bv8), and some MMPs." (PMID 34025641, 2021). "MDSCs are recruited to tumor sites through GM-CSF; monocyte chemoattractant protein 1 (MCP1); CXCL1, 2, 5, and 12; IL-8; CSF1; prokineticin 2 (Prok2); CCL2; S100A8/9; and other factors derived from the TME47,61,62." (PMID 34403220, 2021). "The neutrophils secrete several inflammatory, immunoregulatory and angiogenic factors, including NE, PR3, CathG, MMPs, VEGF, Bv8 (prokineticin 2), oncostatin M, IL-1β, TGFβ2, BMP2 and HGF, that modulate the tumor microenvironment and affect tumor growth." (PMID 34572138, 2021). "With regard to the tumor stage, we found that RFS duration was significantly shorter in patients with PROK2-positive tumors than in those with PROK2-negative tumors among patients with stage II (p = 0.020) and III CRC (p = 0.023)." (PMID 30046389, 2018). "In addition to supporting tumor growth, TANs contribute significantly to tumor angiogenesis by releasing proangiogenic factors such as VEGF, prokineticin-2 (Bv8/Prok2), and fibroblast growth factor 2 (FGF2)." (PMID 40805288, 2025). "In addition, by secreting vascular endothelial growth factor (VEGF), prokineticin 2 (Prok2) and matrix metalloproteinase 9 (MMP9) MDSCs foster tissue remodelling and angiogenesis thus sustaining tumour growth." (PMID 36691794, 2023). "Interestingly, PROK2 is known to sequester the promoter of HIF-1, alluding to the hypoxic tumour environment (resonating with MSK2 activities above) and to alter the extracellular matrix, potentially controlling angiogenesis." (PMID 33121134, 2020). "Cancer‐associated fibroblasts (CAFs) can induce the activation of neutrophils and avoid its apoptosis, while the activation of neutrophils can induce the formation of tumor blood vessels through the secretion of VEGFA, PROK2, and other vascular endothelial growth factors." (PMID 32786144, 2020). "Furthermore, PROK2 expression was positively correlated with tumor-node-metastasis (TNM) stage, and patients with an advanced TNM stage showed higher PROK2 expression." (PMID 30046389, 2018). "Third, the aim of this study was to identify novel molecular biomarkers with prognostic potential, regardless of their function; thus, we did not explore the biological mechanisms of PROK2 in tumor development." (PMID 30046389, 2018). "Moreover, the other genes in the deletion, EIF4E3, RYBP, PROK2, and GPR27 all mediate activities that intersect with the PI3K pathway in a potentially tumor suppressive manner." (PMID 29057879, 2017). "Gr‐1+CD11b+ cells also promoted tumor angiogenesis through the G‐CSF/STAT3/prokineticin 2 (Bv8) axis, while anti‐BV8 treatment could significantly reduce the tumor volume and decrease the number of Gr‐1+CD11b cells and their activity, indicating the positive role of MDSCs in tumor angiogenesis." (PMID 40452814, 2025). "In contrast, the pro-tumor TANs have higher levels of Arginase 1 (Arg1), CD206, Ym1, IL-6, CCL17, CXCR4, neutrophil elastase (NE), matrix metalloproteinase 9 (MMP9), vascular endothelial growth factor (VEGF), and the neuropeptide prokineticin 2 (PROK2, also known as Bv8)." (PMID 37496019, 2023). "Taken together, PROK2 may be another interesting AAE6 target, as its dual role in HIF-1 signaling and immune biology may contribute to the “success” of this sub-lineage in tumour development." (PMID 33121134, 2020).
tumor (continued). "In addition, we found that the number of neutrophils continuously increased, and these cells expressed high levels of Mmp9, Prok2, Vegfa, and Nos2, but not tumor suppressors." (PMID 32709844, 2020).